EPHA4 (EPH receptor A4)
Description:
Receptor tyrosine kinase which binds membrane-bound ephrin family ligands residing on adjacent cells, leading to contact-dependent bidirectional signaling into neighboring cells. The signaling pathway downstream of the receptor is referred to as forward signaling while the signaling pathway downstream of the ephrin ligand is referred to as reverse signaling. Highly promiscuous, it has the unique property among Eph receptors to bind and to be physiologically activated by both GPI-anchored ephrin-A and transmembrane ephrin-B ligands including EFNA1 and EFNB3. Upon activation by ephrin ligands, modulates cell morphology and integrin-dependent cell adhesion through regulation of the Rac, Rap and Rho GTPases activity. Plays an important role in the development of the nervous system controlling different steps of axonal guidance including the establishment of the corticospinal projections. May also control the segregation of motor and sensory axons during neuromuscular circuit development. In addition to its role in axonal guidance plays a role in synaptic plasticity. Activated by EFNA1 phosphorylates CDK5 at 'Tyr-15' which in turn phosphorylates NGEF regulating RHOA and dendritic spine morphogenesis. In the nervous system, also plays a role in repair after injury preventing axonal regeneration and in angiogenesis playing a role in central nervous system vascular formation. Additionally, its promiscuity makes it available to participate in a variety of cell-cell signaling regulating for instance the development of the thymic epithelium. During development of the cochlear organ of Corti, regulates pillar cell separation by forming a ternary complex with ADAM10 and CADH1 which facilitates the cleavage of CADH1 by ADAM10 and disruption of adherens junctions (By similarity). Phosphorylates CAPRIN1, promoting CAPRIN1-dependent formation of a membraneless compartment (By similarity).
Synonyms: EK8; hEK8; SEK; TYRO1
Tractability: Small molecule: an approved drug acts on it; a structure with a bound ligand is known; a high-quality ligand is known; it has a high-quality binding pocket; it belongs to a druggable protein family. Antibody: its Gene Ontology location is reachable by antibodies, with high confidence; UniProt places it where antibodies can reach, with medium confidence; UniProt predicts a signal peptide or a membrane-spanning region. PROTAC: ubiquitination databases record sites on it; its protein half-life has been measured; a small molecule that binds it is known.
Target class: Tyrosine protein kinase Eph family; Protein Kinase; TK protein kinase group; Kinase; Enzyme
Chemical probes: ML040
Gene: Protein-coding gene on chromosome 2 (221,418,027 to 221,574,202, reverse strand). Ensembl gene ENSG00000116106.
Subcellular location: Cell membrane; Cell projection, axon; Cell projection, dendrite; Postsynaptic density membrane; Early endosome; Cell junction, adherens junction
Pathways (Reactome):
Developmental Biology: EPH-Ephrin signaling; EPH-ephrin mediated repulsion of cells; EPHA-mediated growth cone collapse; Somitogenesis
Gene Ontology:
Molecular function: DH domain binding; ephrin receptor activity; kinase activity; PH domain binding; protein binding; protein tyrosine kinase binding; amyloid-beta binding; GPI-linked ephrin receptor activity; protein tyrosine kinase activity; transmembrane-ephrin receptor activity; ATP binding; ephrin receptor binding; identical protein binding; protein kinase activity; transmembrane receptor protein tyrosine kinase activity
Biological process: ephrin receptor signaling pathway; negative regulation of cell adhesion; negative regulation of cell migration; negative regulation of cellular response to hypoxia; negative regulation of epithelial to mesenchymal transition; negative regulation of ERK1 and ERK2 cascade; positive regulation of amyloid precursor protein catabolic process; positive regulation of amyloid-beta formation; positive regulation of cell adhesion; positive regulation of cell migration; positive regulation of cell population proliferation; positive regulation of leukocyte adhesion to arterial endothelial cell; protein stabilization; axon guidance; cellular response to amyloid-beta; corticospinal tract morphogenesis; fasciculation of motor neuron axon; fasciculation of sensory neuron axon; motor neuron axon guidance; negative regulation of axon regeneration; negative regulation of long-term synaptic potentiation; negative regulation of neuron projection development; negative regulation of translation; neuron projection fasciculation; neuron projection guidance; and 14 more
Cellular component: axon; cytoplasm; dendrite; dendritic shaft; dendritic spine; early endosome; early endosome membrane; plasma membrane; postsynaptic density membrane; adherens junction; axon terminus; axonal growth cone; cell body; cell surface; filopodium; glutamatergic synapse; membrane; mitochondrial outer membrane; neuromuscular junction; perikaryon; postsynaptic density; postsynaptic membrane; presynaptic membrane; Schaffer collateral - CA1 synapse
Genetic constraint (gnomAD): Loss-of-function variants: 17 observed, 99.77 expected, observed/expected ratio (o/e) 0.17, 90% interval 0.12 to 0.26. The upper end of that interval is the gene's LOEUF score, 0.26, which puts it in group 1 of 6, group 1 being the genes least tolerant of losing a copy. Missense variants: 882 observed, 1,276.2 expected, observed/expected ratio (o/e) 0.69, 90% interval 0.65 to 0.73. Synonymous variants: 436 observed, 469.23 expected, observed/expected ratio (o/e) 0.93, 90% interval 0.86 to 1.01.
Homologues: Orthologues: chimpanzee EPHA4 (100% identical), macaque EPHA4 (99% identical), dog EPHA4 (99% identical), rabbit EPHA4 (99% identical), mouse Epha4 (99% identical), rat Epha4 (99% identical), pig EPHA4 (98% identical), guinea pig EPHA4 (98% identical), tropical clawed frog epha4 (89% identical), zebrafish epha4a (82% identical). Paralogues in human: EPHA5 (65% identical), EPHA3 (63% identical), EPHA7 (62% identical), EPHA6 (61% identical), EPHB1 (59% identical), EPHB2 (58% identical), EPHB3 (57% identical), EPHA8 (57% identical), EPHA2 (50% identical), EPHB4 (50% identical), EPHA10 (46% identical), EPHA1 (43% identical), and 41 more.
Diseases named in the same sentence as EPHA4 in open-access papers:
EPHA4 is named in the same sentence as 142 diseases in open-access papers, as found by Europe PMC text mining. Sharing a sentence is not in itself a finding about the gene and the disease. The quoted sentences say what the papers report.
breast cancer (28 papers, 2011 to 2025). A primary or metastatic malignant neoplasm involving the breast. "Transforming growth factor-beta (TGFβ) signalling from EphA4 has been linked to breast cancer cell growth, motility, and penetration." (PMID 36830852, 2023). "The upregulation of EphA4 and EphA7 receptors in breast cancer was also associated with poor survival." (PMID 36830852, 2023). "EphA4, in particular, has been shown to be associated with proliferation, migration and invasion of breast cancer cells, in the context of transforming growth factor-beta (TGFb) signalling." (PMID 33430066, 2021). "To better evaluate the prognostic value of EPHA4 in breast cancer, we also assessed the association of EPHA4 mRNA levels and patients outcomes using GOBO online database and relapse-free survival (RFS) as an end-point." (PMID 29101386, 2017). "To further evaluate the role of EPHA4 in breast cancer, next we investigated the association between EPHA4 mRNA levels and tumor grade, stage, molecular subtypes and patient outcome using GOBO and ONCOMINE databases." (PMID 29101386, 2017). "In this study, we provided the novel evidence that host EphA4 deficiency inhibited murine breast cancer growth and metastasis by reducing the EphA4‐GH receptor (GHR)‐IGF1 and/or EphA4‐IGF1 activities, which lead to decreasing IGF1 production." (PMID 26923183, 2016). "An increased expression of EphA4, EphA7 and EphA10 receptors was also found in breast cancer, which is associated with poor prognosis, and EphA4 is reported to promote breast cancer cell proliferation, migration, and invasion via the transforming growth factor-beta (TGFβ) signalling pathway." (PMID 36830852, 2023). "Moreover, TMA analysis of two independent human breast cancer cohorts also revealed a positive association between hRNase 1 and phospho-EphA4 expression." (PMID 33986289, 2021). "Notably, high hRNase 1 level in plasma samples is positively associated with EphA4 activation in tumor tissues from breast cancer patients, highlighting the pathological relevance of the hRNase 1-EphA4 axis in breast cancer." (PMID 33986289, 2021). "Importantly, we found significant co-expression of EPHA4 and the TGFβ receptor type-2 (TGFβR2) in breast cancer subtypes associated with increased tumor relapse and drug resistance." (PMID 29101386, 2017). "Finally, our results using large datasets from breast cancer patients revealed a significant association between high EPHA4 mRNA expression levels and poor patient outcome, as illustrated by the shortened relapse free survival in a large cohort of 1881 breast cancer patients." (PMID 29101386, 2017). "For instance, RNase1 has been shown to interact with EphA4 in breast cancer, RNase5 with EGFR in pancreatic cancer, RNase4 with AXL in prostate cancer, RNase7 with ROS1 in liver cancer, respectively." (PMID 40246819, 2025). "Given that EphA4 serves as a cognate receptor of RNase1 in breast cancer, furthering our understanding of EphA4 on T cells is worth pursuing to expand the development of cancer treatments by targeting the RNase1-EphA4 axis in the immune system." (PMID 37416781, 2023). "Studies in breast cancer showed that secretory RNase1 binds to and activates EphA4 signaling and the RNase1-EphA4-activating axis promotes stem cell-like properties and tumor growth in nude mouse models." (PMID 37416781, 2023). "Eph-mediated interaction between cancer stem cells (CSCs) and TAMs has also been described in breast cancer, mediated by EphA4." (PMID 36830852, 2023). "Overexpression of EPHA4 and EPHA7 has been associated with worse prognosis in breast cancer as well as glioma." (PMID 35204461, 2022). "Elevated serum hRNase 1 binds to EphA4 and triggers EphA4 signaling in an autocrine/paracrine manner, which in turn promotes breast cancer initiation via the IKK/NF-κB and MEK/Erk activating pathways." (PMID 33986289, 2021).
breast cancer (continued). "Here, the authors report an alternative function of hRNase 1 as a secretory ligand of Eph receptor EphA4 to enhance breast cancer stemness and promote breast tumour initiation." (PMID 33986289, 2021). "The expression of EphA4 and EphA7 receptors was also found to be upregulated in breast cancer, which correlated with a worse prognosis." (PMID 33430066, 2021). "The discovery of hRNase 1 as a secretory ligand of EphA4 that enhances breast cancer stemness suggests a potential treatment strategy by inactivating the hRNase 1-EphA4 axis." (PMID 33986289, 2021). "Both EphA2 and EphA4 are overexpressed in numerous malignancies, including gastric cancer, breast cancer, colon cancer, and prostate cancer (17, –, 24)." (PMID 30782663, 2019). "Overexpression of EphA2 and EphA4 has been reported in gastric cancer, breast cancer, colon cancer, and prostate cancer (17, –, 24)." (PMID 30782663, 2019). "The use of Eph-signaling to potentiate the pro-migratory effects of other pathways supports our results showing that TGFβ increases EPHA4 expression to mediate its pro-migratory effects on breast cancer cells." (PMID 29101386, 2017). "Consistently, high levels of EPHA4 correlate with a reduced overall survival in breast cancer patients." (PMID 28341962, 2017). "We also identified an essential role for EPHA4 in mediating the pro-migratory effects of TGFβ in breast cancer cells." (PMID 29101386, 2017). "All together, these results highlight a novel role for EPHA4 in TGFβ-mediated cell migration in basal breast cancer." (PMID 29101386, 2017). "We further addressed the mechanism and found EPHA4 to be required for TGFβ-mediated cell migration in breast cancer through TGFβ-induced short term and long term activation of RhoGTPases." (PMID 29101386, 2017). "In this study, we identified the Ephrin type-A receptor 4 (EPHA4) as a novel target of TGFβ in breast cancer." (PMID 29101386, 2017). "We also defined strong correlation between high EPHA4 expression, tumor stage and poor prognosis in basal-like breast cancer." (PMID 29101386, 2017). "This further highlights the important role of EPHA4 in this highly aggressive and more metastatic breast cancer subtype." (PMID 29101386, 2017). "Together, this study highlight the important role of the TGFβ/EPHA4 signaling axis in mediating tumor aggressiveness and poor patient survival in human breast cancer." (PMID 29101386, 2017). "TGFβ strongly induced EPHA4 protein levels in all basal breast cancer cell lines, while decreasing its expression in the two luminal subtypes (MCF7 and BT474)." (PMID 29101386, 2017). "Together, these results define the TGFβ/EPHA4 signaling axis as a critical regulator of breast cancer cellular migration, tumor aggressiveness and poor patient outcomes and highlight EPHA4 as a potential new prognostic marker for basal-like breast tumors." (PMID 29101386, 2017). "We isografted 4T1 breast cancer cells into both EphA4‐knockout and control wild‐type female littermate mice." (PMID 26923183, 2016). "Among the family members, EPHA2 and EPHB4 are the most studied in breast cancer and additionally EPHA4, EPHA7 and EPHB6 emerged as promising clinical candidates in an expression profile of the individual EPH and ephrin family members." (PMID 26870995, 2016). "In breast cancer, elevated RNA expression of EphA4 had significant prognostic value, as did EphA2, EphA7, and EphB4." (PMID 23738943, 2013). "These analyses confirmed the relevance of EphA2 and EphB4 to human breast cancer progression, and uncovered significant correlations for EphA4, EphA7, and EphB6, which were previously under-investigated in breast cancer." (PMID 21935409, 2011). "Our previous study found that RNase1 is a ligand of EPHA4 in breast cancer cells." (PMID 40246819, 2025). "Besides this, ID4, SEMA3F, FOXD, KCNK5, WNK4 and ECM1 associate with chemoresistance origin and SOX5, ITM2A, SNCG, EPHA4, NTS, FGFR2 and ENPEP associate moreover with breast cancer tumorigenesis." (PMID 37239828, 2023).
breast cancer (continued). "Notably, ephrin A4 (EphA4) is upregulated in breast cancer stem-like cells (CSCs), and EphA4-mediated juxtacrine signaling maintains the stem cell state through their interactions with tumor-associated monocytes/macrophages and CSCs30." (PMID 33986289, 2021). "Together, these positive correlations between hRNase 1 level, EphA4 activation, and stem-like cell population supported the pathological relevance of the hRNase 1–EphA4 axis in tumor initiation with potential clinical implications for breast cancer treatment." (PMID 33986289, 2021). "In basal breast cancer cells, the TGFβ-induced cell migratory effects observed in parental cells and cells transfected with the scrambled siRNA were blocked in cells transfected with the EPHA4 siRNA." (PMID 29101386, 2017). "Interestingly, EPHA4 expression was significantly higher in the highly aggressive basal-like breast cancer subtypes compared to luminal A, luminal B and Her-2 enriched subtypes (P < 0.00001)." (PMID 29101386, 2017). "These indicate that EPHA4 regulate specific functions of TGFβ, such as cell migration in invasive breast cancer cells without affecting the other arm of the TGFβ signaling pathway, such as tumor suppression in luminal and early breast carcinoma." (PMID 29101386, 2017). "Our findings suggested that targeting EphA4 may lead to a novel inhibiting effect combined with other regulators in breast cancer therapy, especially where the tumor cell proliferation and survival are dependent on local tissue IGF1 production." (PMID 26923183, 2016). "We evaluated protein expression of EphA2, EphA4, EphA7, EphB4, and EphB6 in human breast cancer tissue microarrays (TMA) in which we could distinguish expression in tumor epithelium from stromal components, including endothelium." (PMID 21935409, 2011). "Deregulated expression or aberrant increased activity of EphA4 is reported in various human diseases such as Alzheimer’s disease (AD), amyotrophic lateral sclerosis, and cancers including breast cancer and pancreatic cancer, suggesting that EphA4 may be a promising drug target." (PMID 29743517, 2018). "Thus, new strategies based on targeting EPHA4 in metastatic breast cancer could prove useful and very specific as they will presumably not be interfering with the TGFβ tumor suppressive effects in normal and non-invasive cells." (PMID 29101386, 2017). "EPHA4 is a receptor involved in cancer cell proliferation in breast cancer cells through AKT signaling, where downregulation of EPHA4 decreased proliferation and increasing EPHA4 increased proliferation." (PMID 37621654, 2023). "Concerning breast cancer human material in general, some recent studies have attempted to link the expression of EPHA2, EPHA4, and EPHA7 with clinicopathologic parameters and/or survival." (PMID 35204461, 2022). "In the UALCAN database, the mRNA expression of EPHA1, EPHA10, EFNA1, EFNA3, and EFNA4 was significantly higher, whereas that of EPHA2, EPHA4, EPHA5, and EFNA5 was significantly lower in breast cancer tissues than in paracancerous tissues." (PMID 33977106, 2021). "Although we found that EPHB2 was the most promising candidate in our breast cancer cohorts, EPHB2 together with EPHB6, EPHA2, EPHA4 and the ligands EFNB1 and EFNB2 were important to define prognostic relevant clusters." (PMID 26870995, 2016). "Given the important roles of FOXM1, EPHA4 and EPHA7 on breast cancer outcome, FOXM1 and miR-135a were good candidates for a siRNA knockdown study." (PMID 27528030, 2016). "Furthermore, Western blot analysis for EPHA2, EPHA4, and EPHA7 was performed in three different human breast cancer cell lines." (PMID 35204461, 2022). "Together, these data indicate that TGFβ significantly induces EPHA4 expression, specifically in BLBC and strongly suggest that EPHA4 acts downstream of TGFβ, to maintain or contribute to the highly metastatic profile in these basal subtype breast cancer cells." (PMID 29101386, 2017).
breast cancer (continued). "Finally, our results also highlight a strong and significant correlation between EPHA4 and TGFBR2 mRNA expression levels (r = 0.17, P < 0.0001) in more than 5000 breast cancer patients samples obtained from Breast Cancer Gene-Expression Miner v4.0 database." (PMID 29101386, 2017). "Especially EPHA2, EPHA4, EFNB1, EFNB2, EPHB2, and EPHB6 and their co-expression in breast cancer." (PMID 26870995, 2016). "A previous research in breast cancers reported that the direct binding between tumor cells and macrophages mediated by CD11b/CD90 and Ephrin/EphA4 induced the EMT of breast cancer cells, thus establishing a cancer stem cell niche in a juxtacrine dependent manner." (PMID 27888616, 2016). "hRNase 1 induced phosphorylation of EphA4, but not of EphA3 or EphA5, and activation of phospholipase C-γ (PLCγ), a downstream signaling molecule of EphA430, in BT-549 basal-like breast cancer cells." (PMID 33986289, 2021). "Thus, we next studied whether activation of the TGFβ receptor in basal breast cancer cells could lead to an accumulation of active, GTP-loaded GTPases in control breast cancer cells (scrambled shRNA) versus cells stably overexpressing the EPHA4 shRNA." (PMID 29101386, 2017).